MGAT3-AS1 (MGAT3 antisense RNA 1)
Synonyms: TapSAKI
Gene: Long non-coding RNA gene on chromosome 22 (39,475,807 to 39,476,822, reverse strand). Ensembl gene ENSG00000227188.
Diseases named in the same sentence as MGAT3-AS1 in open-access papers:
MGAT3-AS1 is named in the same sentence as 2 diseases in open-access papers, as found by Europe PMC text mining. Sharing a sentence is not in itself a finding about the gene and the disease.
MGAT3-AS1 shares sentences with these, for which no sentence is quoted: acute kidney injury (5 papers); Sepsis (3).